PPARG (peroxisome proliferator activated receptor gamma)
Diseases named in the same sentence as PPARG in open-access papers (continued):
Sharing a sentence is not in itself a finding about the gene and the disease.
colorectal cancer (continued). "Peroxisome proliferators-activated receptor PPARγ not only plays an important role in fat metabolism, but also a significant role in regulating the radiosensitivity of colorectal cancer cells." (PMID 37170184, 2023). "PPARγ inhibits colorectal cancer by regulating cell differentiation and the expression of cell cycle regulators." (PMID 37251321, 2023). "In colorectal cancer, emerging evidence has shown that PPARG signaling is downregulated due to the regulatory actions of EZH2 and HDAC1." (PMID 36142846, 2022). "CLAs induce macrophage- and T-cell-producing TGF-β via PPARγ activation, which enhances colorectal cancer progression." (PMID 35954274, 2022). "For example, PPARγ was identified as a miR-130b direct target in colorectal cancers, and miR-130b was also identified as an independent prognostic biomarker in glioma patients by targeting PPARγ." (PMID 36082081, 2022). "It has been reported that, in colorectal carcinoma cells, PPARγ stimulates the expression of PTEN and inhibits PI3K activity." (PMID 36101378, 2022). "The role of PPARγ in the development of normal colon epithelium and colorectal cancers is not completely understood and seems to be dual." (PMID 33716977, 2021). "In Colorectal cancer, studies with Caco-2, a common colorectal cancer cell line, have shown that activation of autophagy occurs following treatment with PPARγ agonist rosiglitazone." (PMID 32998777, 2020). "In patients, PPARγ plays a role in i) pregnancy related adaptations of lipid metabolism and ii) as target in colorectal cancer (CRC)." (PMID 32773037, 2020). "The mutations in helix H3 of PPARγ LBD included C285Y, Q286P, R288H and S289C identified in patients with colorectal cancer, F287Y, R288C from patients with skin cancer, Q286E from a patient with bladder cancer and R280C from a patient with uterine cancer." (PMID 33266062, 2020). "This homology is of particular interest, as human PPARγ plays a role in i) pregnancy related adaptations of lipid metabolism and ii) as target in colorectal cancer (CRC)." (PMID 32773037, 2020). "In humans and rats, SP1, SMADs, and hypoxia-inducible factor-1 activate transcription via direct binding to the promoter region of NT5E, whereas peroxisome proliferator-activated receptor gamma (PPAR-γ) suppresses its transcription in human colorectal cancer." (PMID 32604872, 2020). "Here, we analyzed a series of chiral phenoxyacetic acid analogues for their ability to inhibit colorectal cancer (CRC) cells growth by binding PPARγ as partial agonists as assessed in transactivation assays of a PPARG-reporter gene." (PMID 30931956, 2019). "Our previous review summarized the role and action mechanisms of PPARγ in colorectal cancer, but the role of PPARγ in cancer is still debated." (PMID 29599799, 2018). "PPARγ agonists can halt the tumor cell growth cycle of the colorectal cancer, induce the differentiation of intestinal cancer cells, change the morphology of tumor cells, and promote tumor cell apoptosis to achieve the antitumor effect." (PMID 29483923, 2018). "Active KRAS oncogene downregulates the peroxisome proliferator-activated receptor gamma (PPARγ), which has been proposed as a marker for colorectal cancer survival." (PMID 30181486, 2018). "Human colorectal cancer cells express abundant PPARγ, but its inhibitory function is very low, signifying a defect in the PPARγ pathway." (PMID 29799499, 2018). "It was first analyzed the autophagic status of Caco-2 colorectal cancer cell line treated with PPARγ agonist and antagonist." (PMID 28932171, 2017). "Past literature reported that the effect of miR-130b in colorectal cancer are due to PPARγ suppression that in turn deregulates PTEN, E-cadherin and so on28." (PMID 28165066, 2017). "We genotyped four polymorphisms in four genes (IL1B, TNF, PPARG, and PPARGC1A) and calculated the dietary inflammatory index (DII) in a case-control study with 701 colorectal cancer patients and 1,402 controls." (PMID 28051997, 2017).
colorectal cancer (continued). "In this work, we evaluated the involvement of autophagy and PPARγ with cell proliferation, cell death, lipid droplets formation, cell cycle, ROS production and cancer stem cells profile using colorectal cancer cells as a model." (PMID 28932171, 2017). "A study of colorectal cancer cells demonstrated that PPARγ regulates KLF4 transcription by directly binding to the KLF4 promoter." (PMID 27483249, 2016). "For example, in colorectal cancer cell lines, miR-130b directly targeted peroxisome proliferator-activated receptor γ (PPARγ), which regulates some key mediators of cell proliferation, such as P21, cyclin A, and PTEN, thus increasing cell proliferation." (PMID 27391066, 2016). "To better understand the underlying gene regulatory functions of LXRs and PPARG that lead to metabolic reprogramming in cancer cells, we performed a comprehensive genome-wide analysis of LXR and PPARG activity in HT29 colorectal cancer cells." (PMID 27401066, 2016). "We evaluated the proliferative and metabolic effects of LXRs and PPARG in HT29 colorectal cancer cells with several cellular assays." (PMID 27401066, 2016). "Many naturally occurring elicit their chemopreventive actions against inflammation-induced colorectal cancer through PPARγ activation." (PMID 27445823, 2016). "UHRF1 coordinates PPARG (peroxisome proliferator-activated receptor γ) epigenetic silencing and mediates colorectal cancer progression." (PMID 25272010, 2014). "More recently, our group identified in sporadic colorectal cancers two novel PPARG transcripts harboring a read-through in intron 4, named γ2ORF4 and γ3ORF4, displaying the same 5′UTRs of PPARG2 and PPARG3, respectively." (PMID 24790595, 2014). "Previous studies reported that miR-130b led to PPARγ suppression that in turn promotes EMT progression in colorectal cancer." (PMID 25387077, 2014). "Anyway, decreased PPARγ expression compared with adjacent normal colonic mucosa is detected in a number of colorectal cancer patients, and PPARG inactivation seems to play a role in colorectal cancer progression, although the events involved are not yet clear." (PMID 23028383, 2012). "PPARγ agonist GW7845 induced cell death through downregulation of survivin in colorectal cancer cells." (PMID 23024650, 2012). "Increasedexpression of PPARγ in human colorectal cancer cell lines treated withtroglitazone, a PPARγ agonist, is associated with increased differentiation." (PMID 19390648, 2009). "The PPARγ inhibitor T0070907 can reduce tubulin levels in colorectal cancer cell lines and suppress tumor growth in a murine xenograft model." (PMID 18509498, 2008). "PPARγ expression, as well as ODC and SSAT mRNA levels were significantly higher (p < 0.05; Mann Whitney test) in colorectal carcinoma samples expressing K-ras mutation as compared to non mutated K-ras samples." (PMID 16854216, 2006). "Few studies have investigated the expression of PPARγ in human colorectal carcinoma in relation to normal mucosa." (PMID 16854216, 2006). "In this direction, we have evaluated the PPARγ expression and its relationship with polyamine metabolism in tissue samples from 40 patients operated because of colorectal carcinoma." (PMID 16854216, 2006). "PPARG is reported to be a promising target for patients diagnosed with colorectal cancer (CRC)." (PMID 40500799, 2025). "Furthermore, reduced FABP1 expression has been documented in MSI-high (microsatellite instability-high) colorectal cancers, potentially attributable to the IFNγ-mediated suppression of PPARG within their highly immunoreactive microenvironment." (PMID 40694956, 2025). "The purpose of this investigation was to determine whether ZDHHC6 interacts with PPARγ in additional colorectal cancer cells." (PMID 39148124, 2024).
colorectal cancer (continued). "Together, we discovered a previously unknown harmful connection between ZDHHC6 and the variables that regulate the production of fatty acids and the balance of lipid oxidation, specifically related to PPARγ, in patients with colorectal cancer." (PMID 39148124, 2024). "The studies presented above unambiguously demonstrated that ZDHHC6 is a significant palmitoyltransferase that plays a role in the occurrence of palmitoylated PPARγ, and the activity of this enzyme was found to have a favorable correlation with the progression of colorectal cancer." (PMID 39148124, 2024). "However, hsa-miR-548-family seems to embrace a very close relationship with PPARG from our study, and it belongs to the top down-regulated colorectal cancer from Josef Horak’s research." (PMID 37857015, 2023). "There is also evidence suggesting that PPARγ activation may have therapeutic benefits in colorectal cancer and other malignancies." (PMID 37645246, 2023). "Furthermore, many studies have shown that PPARG plays a vital role in regulating the growth of several different cancers, including prostate, bladder, breast, and colorectal cancer." (PMID 37857015, 2023). "Moreover, NOTCH/HES1 axis inhibition accompanied by PPARγ activation can repress the progression of colorectal cancer via suppressing cancer stem cells." (PMID 36147468, 2022). "The expression of PPARG was negatively correlated with the survival rate of colorectal cancer." (PMID 36033393, 2022). "Consequently, PPARγ deletion, specifically in ILC2s, reduced tumor growth in a mouse colorectal cancer model." (PMID 35954274, 2022). "But the expression of IGF1R, IGF2R, and PPARG was negatively correlated with the number of infiltrated CD8+ T cells in colorectal cancer; the related antidiabetic drugs may produce negative effect on anti-PD1 tumor inhibition." (PMID 36033393, 2022). "In addition to providing energy for the colonocytes, butyrate can suppress NF-κB transcription factor activation and interferon gamma and upregulate PPARγ, which thus withstand colorectal cancer and inflammatory bowel diseases." (PMID 33922589, 2021). "Downstream of steroidal signaling, Eip75B/PPARγ promotes postmitotic cell fate when local signaling is deteriorated and thus might reflect a promising target for future studies in colorectal cancer models." (PMID 32773037, 2020). "Notably, it was reported that 15-Lox-1 and its product activate MAP kinase pathway and subsequently reduced the activity of PPARγ in prostate and colorectal carcinoma cells while 15-Lox-2 and 15(S) HETE suppress MAP kinase pathway." (PMID 31288808, 2019). "Additionally, it is one of the members of the signal transduction of the peroxisome proliferator-activated receptor gamma (PPARγ) pathway in human colorectal cancer cells." (PMID 29799499, 2018). "Attempting to determine the clinical relevance of the epigenetic mechanisms controlling the expression PPARγ and susceptibility to colorectal cancer (CRC) in obese subjects, this study investigated the role of some microRNAs and DNA methylation on the deregulation of PPARγ." (PMID 28878369, 2017). "In addition, Krüppel-like factor 4 (KLF4), a tumor suppressor in HCC, has been reported to be up-regulated by the PPARγ agonist troglitazone and promotes cell cycle arrest in colorectal cancer cells." (PMID 27483249, 2016). "PPARγ has also been identified as an initiator in mediating EMT in colorectal cancer." (PMID 27145370, 2016). "However, in colorectal cancer, both tumor-suppressive and tumor-facilitating functions have been proposed for PPARG." (PMID 27401066, 2016). "Studies on human tumor samples support the hypothesis that PPARγ expression has protective effects in colorectal cancer; patients with PPARγ expression usually showed a better prognosis." (PMID 25866814, 2015). "The role of PPARβ/δ in colorectal cancer is more controversial than that of PPARγ." (PMID 23024650, 2012).
colorectal cancer (continued). "However, the role of PPARγ in gastrointestinal cancers, especially in colorectal cancer, is rather controversial." (PMID 19884989, 2009). "Moreover, there is considerable controversy concerning the effects of thiazolidinedione PPARγ agonists on the two major diseases of the gastrointestinal track: colorectal cancer and inflammatory bowel disease." (PMID 18615192, 2008). "In colorectal cancer, SPP1+ macrophages highly express complement component 1C chain (C1QC), mannose receptor C type 1 (MRC1), signal transducer and activator of transcription 1 (STAT1), and peroxisome proliferator-activated receptor gamma (PPARG), which are associated with macrophage polarization." (PMID 38919629, 2024). "Furthermore, PPARG appears to promote tumour-progressive behaviour in colorectal cancer cell lines." (PMID 38378472, 2024). "We also consolidate autophagy as a key factor for colorectal cancer cells survival in vitro, pointing out a potential side effect of autophagic inhibition as a therapeutic application for this disease and demonstrate a novel regulation of PPARγ expression by inhibition of PI3K III." (PMID 28932171, 2017). "Thus, in addition to pro-apoptotic side effects of Orlistat in colorectal carcinoma cells, Orlistat may also induce anti-inflammatory genes in gut tissue mediated by its PPARγ agonist activity." (PMID 23566279, 2013). "Increased expression of PPARγ stimulates the production of lipids and the development of tumors, together with the activation of ACLY in colorectal cancer (CRC)." (PMID 39148124, 2024). "Although data on IL6 mRNA levels are not shown due to undetectable expression in the SW620 cell line, PPARG and TGFB1 mRNA levels decreased after colorectal cancer tumorsphere generation." (PMID 39336151, 2024). "Once PPARγ was inhibited by ID3, it further promoted ID3 and formed a positive feedback loop to gradually enhance the malignancy of colorectal cancer cells and radiotherapy resistance." (PMID 37170184, 2023). "When ID3 is increased, it inhibits PPARγ protein, and when PPARγ is inhibited by ID3, it further promotes ID3 expression, to gradually enhance the malignancy of colorectal cancer cells and radiotherapy resistance." (PMID 37170184, 2023). "ID3 interacted with PPARγ and form a positive feedback loop to enhance the effect of ID3 on the radiosensitivity of colorectal cancer." (PMID 37170184, 2023). "In contrast, miR-27b-3p accelerated tumor progression via PPARG and HOXA10 in triple-negative breast cancer and colorectal cancer, respectively." (PMID 36306007, 2022). "In colorectal cancer, UHRF1-mediated methylation of a peroxisome proliferator-activated receptor (PPARγ) was shown to be a key determinant of disease progression." (PMID 36077796, 2022). "Recently, a study showed that PPAR expressions are explicitly deregulated in colorectal cancer (CRC), with PPARα and PPARδ being overexpressed, while PPARγ is suppressed in CRC tumor tissues." (PMID 35481240, 2022). "PPARγ is highly expressed in lung and adipose tissue ILC2107 and genetic ablation or pharmacological inhibition of both PPARγ and DGAT1 strongly ameliorated not only ILC2-dependent airway inflammation but also IL-33-mediated colorectal cancer growth." (PMID 36045216, 2022). "MET, NTRK1, and PPARG showed outlier expression in samples from three patients with GEJ adenocarcinoma, colorectal cancer, and urothelial cancer, respectively." (PMID 34385467, 2021). "The administration of ciglidazone, a thiazolidine-based PPARγ agonist, to colorectal cancer cells HT-29 reduces the expression of COX-2, suggesting that the activation of PPARγ suppresses the expression of COX-2." (PMID 34827205, 2021). "Dongmei Zhao showed that miRNA-211 enhances the ability of colorectal cancer cells to invade and migrate by targeting FABP4 via PPARγ." (PMID 34422636, 2021).
colorectal cancer (continued). "Consistently, pharmacological activation of PPARγ increased mRNA and protein expression of OCTN2, and oxaliplatin sensitivity in colorectal cancer SW480 cells." (PMID 34603016, 2021). "Butyrate not only suppressed NF-κB activation, but also modulated the activity and expression of the Peroxisome-Proliferator-Activated-Receptor gamma (PPARγ) and the vitamin D receptor (VDR) in colorectal cancer cells." (PMID 31067776, 2019). "Previous studies have demonstrated that rosiglitazone, a synthetic ligand for PPARγ, upregulates PTEN expression in Caco2 colorectal cancer cells." (PMID 23024650, 2012). "More than half of these were in or near several genes, including cadherin 9 type 2 (CDH9) on 5p14, nuclear receptor subfamily 5, group A gene (NR5A2) at 1q32, gene deleted in colorectal carcinoma (DCC) on 18q21, and PPARG on 3p25." (PMID 17903296, 2007). "The PPARγ, ODC and SSAT mRNA levels were significantly higher in colorectal carcinoma than in normal surrounding mucosa." (PMID 16854216, 2006). "Furthermore, patients who have colorectal cancer (CRC) and exhibit high expression levels of both ZDHHC6 and PPARγ tend to have an unfavorable prognosis and lower overall survival rates." (PMID 39148124, 2024). "Currently, the specific role of PPARG in patients with colorectal cancer (CRC) is not fully understood." (PMID 38378472, 2024). "Although this study does not address the role of PPARG in the development of colorectal cancer, it provides strong data that PPARG expression in tumors is associated with increased survival." (PMID 32813759, 2020). "It was previously shown that UHRF1 negatively regulates PPARγ and increases proliferation, migration, and clonal formation in colorectal cancer cells lines, and the molecular mechanism revealed that UHRF1 recruits PPARγ promoter and accelerates DNA methylation and repressive histone modification." (PMID 31428652, 2019). "Finally, miR-145, which is downregulated in colorectal cancer cells (Caco2, Sw480, HCT116, and HT29) and colorectal tumor tissues, is induced by the PPARγ agonist (i.e., rosiglitazone) via direct binding of PPARγ to PPRE in the promoter encoding pre-miR-145." (PMID 28167956, 2017). "The autophagic pathway regulation by PPARγ activation and the PPARγ expression modulation by autophagy in colorectal cancer cells have not yet been reported." (PMID 28932171, 2017). "In colorectal cancer, we found that the cofactors of TFAP2A were PPARG and SP1." (PMID 28684851, 2017). "Additionally, previous reports have demonstrated that miR-130b regulated EMT through targeting PPARG in HCC, colorectal cancer and glioma and through targeting DICER1 in endometrial cancer." (PMID 28107197, 2017). "In colorectal cancer, endocannabinoids and synthetic cannabinoids were able to induce apoptosis and inhibit carcinogenesis by mechanisms involving both CB receptors, TRPV1 channels and PPARγ-pathway." (PMID 26539529, 2015). "PPARG epigenetic silencing has been found to be coordinated by ubiquitin-like with PHD and RING finger domains 1 (UHRF1), a member of a subfamily of RING-finger-type E3 ubiquitin ligases, which mediates colorectal cancer progression." (PMID 23028383, 2012). "In a large series of primary colorectal cancers, about 60% of tumors showed PPARγ upregulation, whereas 35% of the tumours showed lower PPARγ levels compared to the nontumorous normal mucosa." (PMID 23028383, 2012). "In conclusion, our data demonstrated a close relationship between PPARγ and SSAT in human colorectal cancer and this could represent an attempt to decrease polyamine levels and to reduce cell growth and tumour development." (PMID 16854216, 2006). "In conclusion, our data show a close relationship between PPARγ and SSAT in human colorectal cancer and this could represent an attempt to decrease polyamine levels and to reduce cell growth and tumour development." (PMID 16854216, 2006). "The same methylation pattern is found in PPARγ negative colorectal cancer cell lines." (PMID 23028383, 2012).